CD4 (CD4 molecule)
Diseases named in the same sentence as CD4 in open-access papers (continued):
Sharing a sentence is not in itself a finding about the gene and the disease.
parasitemia (continued). "Herein, using the mouse model of non-lethal P. yoelii (Py) infection, we reveal that the kinetics of blood parasitemia as well as CD4+ T follicular helper (TFH) and germinal center (GC) B cell responses are indistinguishable between PD-1-/-, PD-L1-/- and WT mice." (PMID 33519801, 2020). "Recently, new subset of CD4+T named as T helper 9 cells that express the prototypical interleukin-9 (IL-9) cytokine have been recognized in human and mice models during different parasitic infections." (PMID 32243446, 2020). "Short-lived CD4+ TEM cells are believed to play a key protective role in controlling parasitemia." (PMID 31718574, 2019). "Previously, we observed that CD4+Foxp3+ Tregs increase significantly in the spleen of infected B6 mice during acute P. chabaudi AS infection followed by a significant increase in effector CD4+T-bet+IFN-γ+ Th1 cells around the time of peak parasitemia." (PMID 30915078, 2019). "Therefore, since TLR11xCasp1/11-/- mice have intact IL-18R signaling, we examined if exogenous IL-18 administered to TLR11xCasp1/11-/- mice during parasite infection would be sufficient to restore CD4+ TH1-derived IFN-γ responses." (PMID 31194844, 2019). "Furthermore, during parasite infection, CD4+ T cells are capable of secreting Th1 cytokines (e.g., IFN-γ), which are crucial for macrophage activation and subsequent inhibition of the parasite." (PMID 30911415, 2019). "We followed the number of IL-4- and IL-13-expressing CD4 T cells that appear in the draining lymph node and subsequent type 2 inflammatory response in the skin or lung following intradermal priming with allergen or parasite infection, respectively." (PMID 29910811, 2018). "Similarly, TCR-βhiNK1.1+ CD4+ T cells expanded in the spleen after P. chabaudi infection, a rodent model characterized by persistent low-level parasitemia." (PMID 30374346, 2018). "Thus, our results showed that GRAIL expression is induced during acute phase of infection and correlates with the peak of parasitemia and with CD4 T cell hiporesponsiveness." (PMID 28114324, 2017). "Therefore, the requirement of IL-3 produced by CD4+ T cells appears to be common to the basophil recruitment to draining lymph nodes and skin in the parasitic infections, in spite of the difference in the timing of recruitment." (PMID 29085376, 2017). "Furthermore, the adoptive transfer of WT CD4+ T cells was able to reduce parasitemia to WT levels in both Il18r1−/− and Myd88−/− infected mice, in an IFN-γ-dependent way, and to improve survival in both strain." (PMID 28895840, 2017). "In this study, we examined if the effects of parasitic infection could be due to increased IL-5, which not only induce eosinophilia but also as a bystander effect further expands antigen-specific CD4+CD25+ Treg activated by autoantigen and IL-4." (PMID 29163523, 2017). "Supporting this idea, mice transferred with B6 CD4 T cells at 20 days p.i. containing both Th1 and Tfh cells showed a better control of the first and second parasitemia peaks than those transferred with the P2rx7-/- counterparts where there is a marked predominance of the Tfh phenotype." (PMID 28859168, 2017). "Skin-resident, IFNγ-producing CD4+ memory T cells protect against Leishmania major re-infection by recruiting circulating T cells and inflammatory monocytes to the site of re-infection, leading to efficient control of parasitic infections." (PMID 29085376, 2017). "While the strength and significance of this relationship was less clear in the current study, it is supported by our previous finding that prevalence of asymptomatic parasite infection was reduced in 4-year-old children with high frequencies of Pf-specific TNFα-monofunctional CD4 T cells." (PMID 29097996, 2017). "Similarly, only 1 of 4 PD-1KO mice showed parasitemia on depletion of CD4+ T cells indicating limited contribution of these cells to long-term protection in the absence of PD-1." (PMID 27217330, 2016).
parasitemia (continued). "However, after self-cured parasite infection, around 40% of CD4+T cells and 60% of CD8+T cells expressed the exhaustion marker PD-1, indicating loss of their functional capacity." (PMID 27900319, 2016). "However, a statistically significant difference in rate of any parasitic infection by type of diarrhea was observed in a CD4 category 200–499 cells/μl (acute diarrhea 26.2 % vs chronic diarrhea 45.2 %; χ2 = 4.99, df = 1, P = 0.03)." (PMID 27165271, 2016). "Sterile injury or transmission of Leishmania via sandfly feeding triggered the recruitment of neutrophils to the skin, where they then served as a “Trojan horse” reservoir for parasite infection, and abrogated vaccine-induced protection by suppressing parasite-specific CD4+ T cell responses." (PMID 27310141, 2016). "Participants with the lower CD4 T cell count had a similar rate of any intestinal parasitic infection (36.2 %) and cryptosporidiosis (15.6 %) compared to those with a CD4 count ≥ 200 cells/μl, but with some type of diarrhea (parasitic infection, 35.6 %; cryptosporidiosis, 10.2 %)." (PMID 27165271, 2016). "The data suggest that they require a higher parasite burden threshold to become pathogenic, because if parasitemia is patent, but controlled by CD4+ T cells, then the CD8+ T cells do not induce a deleterious response." (PMID 27245410, 2016). "In support of previous findings, we showed that either depletion of CD4+ T cells or neutralization of IFN-γ resulted in a significantly elevated peak parasitemia level in IL-27R-/- mice infected with T. congolense, confirming the protective role of CD4+ T cells and IFN-γ during the infection." (PMID 26222157, 2015). "Infected mice from all three groups could effectively control the first wave of parasitemia, although depletion of CD4+ T cells resulted in a significantly higher parasitemia at some time points of infection (p<0.01 or <0.05)." (PMID 26222157, 2015). "But it has also been hypothesized that chronic parasitic infections themselves shift the T-cell populations and decrease the CD4+ cell count." (PMID 25768005, 2015). "However, 2.5 fold (p = 0.04) and 13-fold (p = 0.007) increase in parasitemia percentages relative to naïve and the vaccine groups, respectively, were observed in vaccinated mice depleted of CD4 T cells." (PMID 26505634, 2015). "Although mice depleted of CD8+ T cells suffered from much greater parasitemia from the early phase to its peak, the survivors eliminated the parasites similar to the control mice, whereas the CD4+-T-cell-depleted survivors took longer to recover from infection." (PMID 25760084, 2015). "In summary, our study examines in depth the CD4+ Th2 cell subset repertoire in a chronic parasitic infection and sheds light on the role of these subsets in both the regulation of immune responses in active infection and in the pathogenesis of filarial lymphedema." (PMID 24498448, 2014). "CD4+CD25highFoxp3+ Treg cells followed different kinetics in PB according to parasitemia." (PMID 24465641, 2014). "IFNγ/IL-10 co-producing cells have been described in several parasitic infections and are hypothesized to be important in limiting CD4-mediated pathology, but they may also prevent the development of sterilizing immunity." (PMID 24415936, 2014). "HIV positive patients without ART with CD4+ T-cell counts less than 200 cells/μL had reported higher risk of having diarrhoea independent of parasite infection compared with those having 500 cells/μL and above." (PMID 23991132, 2013). "Given the fundamental importance of CD4+ T-cells in regulating parasite infection and the key role for TGFβ in regulating many aspects of T-cell biology, we analysed TGFβ signalling in T-cells during development of a chronic infection with the helminth Trichuris muris." (PMID 24098124, 2013).
parasitemia (continued). "This was done to investigate the possibility that VV-WR infection induced IL-4 and/or IL-13 to up-regulate IL-4Rα expression on naïve bystander CD8+ T cells similar to what has been reported on naïve bystander CD4+ T cells responding to IL-4 following parasitic infection." (PMID 23383283, 2013). "In our work, B10.PL mice reached a parasitemia peak on day 7 of infection and developed large liver areas with necrotic and apoptotic characteristics, and an intense infiltrate of CD4+ T cells and DCs close to the portal space." (PMID 24312297, 2013). "The association of increased parasitemia with increased viral HIV load and a decreased CD4+ count and CD4+/CD8+ ratio in peripheral blood suggests that these could be analyzed as cofactors of increased parasitemia to further support any intervention." (PMID 21912712, 2011). "After adoptive transfer of chronically simulated or rested CD4 T cells into recipient mice, there were two clear major measurable effects of these cell transfers on parasitemia; a delay in appearance of early parasitemia, and a reduction in peak parasitemia." (PMID 21124875, 2010). "Similarly, an increased rate of mixed parasitic infection was observed at the same lower counts of CD4 T-cells (OR = 3.1; 95% CI 1.1 to 8.9)." (PMID 19765310, 2009). "HIV positive patients with CD4 counts less than 200 cells/μL had reported an excess risk of having diarrhea independent of parasitic infection compared with those having 500 cells/μL and above (OR = 2.7; 95% CI 1.24 to 5.91)." (PMID 19765310, 2009). "However, subsequently there was either a failure of the proliferative response or rapid depletion of CD4+ T cells responding to parasitemia." (PMID 19774084, 2009). "After reviewing the literature and reasoning, we hypothesized that the immunological failure was secondary to CD4+ loss initially by apoptosis in the spleen induced by productive HIV infection and, subsequently, by pyroptosis sustained by parasitic infection in spleen macrophages." (PMID 38491526, 2024). "Persistent parasite infection, including Leishmania major or P. chabaudi, generate recirculating Tcm that do not protect as well as activated Teff or Tem, defined as previously divided CD4+CD62Llo Tem/Teff, or distinguished as CD127− Teff and CD127hi CD44hi CD62Llo CD27− Tem." (PMID 37205446, 2023). "A separate study using Plasmodium yoelii demonstrated that although Rag-/- mice engrafted with WT as opposed to IL-10-deficient CD4+ T cells had increased parasitemia following infection, these mice experienced less severe weight loss and a modest improvement in survival duration." (PMID 36389662, 2022). "A peculiar subset of downregulated CD4+ and CD8+ cells expressed caspase-11 (Scaf11; cluster 10), indicating associated pyroptosis and cell death, potentially by gasdermin-dependent regulation of these cells at an early stage of infection, as found in other parasitic diseases." (PMID 35862712, 2022). "We also performed a ratio of patients’ CD4 counts <200 cells/mL and showed that these people had a 4.07 (95% CI, 1.37–12.12) chance of developing C. cayetanensis and that there was a significant relationship between CD4 counts and parasite infection (p < 0.05)." (PMID 35746750, 2022). "It has already been established over the years that control of parasitemia in bovine babesiosis is dependent on clearance of Babesia-infected erythrocytes by splenic macrophages, which are activated by a fine balance between CD4+ and CD8+ T cells in circulation." (PMID 33187270, 2020). "Interestingly, the measurement of parasitemia indicated a loss of parasite control upon treatment of protected mice with anti-CD4 antibody, but not with anti-CD8 antibody." (PMID 28831137, 2017).
parasitemia (continued). "The risk of diarrhea was observed to increase with decreasing CD4+ T cell count independent of parasitic infection and with HIV patients with counts below 200 cells/μl having excess risk compared to those with CD4+ T cell count above 500 cells/μl (COR = 10.21, p = 0.000)." (PMID 26754404, 2016). "However, although P. chabaudi infection in mice has a prolonged acute parasitemia and a long chronic phase, few PD-1+ effector Tg CD4+ T cells (all CD62Llo, maximum of 5.7% at day 21) were transiently present, and no KLRG-1+ cells were observed (data not shown)." (PMID 21124875, 2010). "The IL-10 from CD4+ and CD8+ cells in parasitic diseases has been described as delaying control while generating immunity due to treatments or vaccination." (PMID 40006676, 2025). "An increase in HIV viral load, a decrease in the number of CD4+ cells/mm3, and the CD4+/CD8+ ratio are cofactors for increased parasitemia that can be used to target the introduction of early, pre-emptive therapy." (PMID 41172398, 2025). "More recently, CD4+ T-cell depletion has been suggested to be caused by pathogenic changes in the spleen due to advanced white pulp disorganization and splenic depletion of CD4+ T cells by apoptosis and pyroptosis secondary to HIV and parasite infection." (PMID 40145085, 2025). "Studies on adjuvants used with the most promising schistosomiasis vaccine antigens have shown that they effectively enhance CD4+ T-cell responses and IFN-γ production, both of which are crucial for protective immunity against parasitic infections." (PMID 41146254, 2025). "However, the ability of SCID mice to control parasitemia also depends on the genetic background of the mice, suggesting that in some genetic backgrounds innate immunity may be of critical importance along with CD4 T cells." (PMID 38392861, 2024). "As for adaptive immunity, a significant increase in the number and activation of both CD4+ and CD8+ T cells was shown in infected mice at the peak of parasitemia, which was consistent with the required time for the engagement of adaptive immunity." (PMID 38892340, 2024). "Vaccinated mice that were depleted of CD4+ T-cells alone or depleted of both CD4+ and CD8+ T-cells developed high parasitemias and succumbed to the infection, similar to the naïve control group." (PMID 37962347, 2023). "This unbalanced CD4+/CD8+ T-cell ratio affects the control of parasites during Pb ANKA infection, which somewhat explains the increased parasitemia in these groups." (PMID 37384220, 2023). "Interestingly, the measurement of parasitemia indicated a loss of protection upon treatment of mice with anti-CD8 (group 2) but not in mice treated with anti-CD4 (group 1) depleting antibodies, while as a control all mice treated with control IgG antibodies (group 3) showed sterile protection." (PMID 37143657, 2023). "It is also known that T cell responses are critical for controlling T. cruzi parasitemia based on knockout models of CD4, CD8, MHC-I, or MHC-II, which all show increased parasitemia and rapid host death upon T. cruzi infection." (PMID 37873108, 2023). "When animals were experiencing peak parasitemia on day 8 p.i., the percentage of CTLA‐4+ cells significantly increased in both TREG and CD4+ T‐cell compartments." (PMID 35475529, 2022). "Lactobacillus fermentum CCM7421 and L. plantarum 17L / 1 increased the numbers of helper CD4 T cells in the epithelium and cytotoxic CD8 T cells in the lamina propria on the 7th day of administration (before parasitic infection)." (PMID 35335620, 2022). "The small molecule 7HP349 adjuvant enhances a Chagas vaccine-stimulated pro-inflammatory cytokine production and cytotoxic activity of CD4+ and CD8+ TEM cells and provides better control of acute parasitemia, as well as parasite persistence." (PMID 34497271, 2021).
parasitemia (continued). "Studies addressing immunologic mechanisms triggered by the most promising vaccine antigens for schistosomiasis have revealed CD4+ T cell responses, and IFN-γ production, as outcomes closely related to protection against the parasite infection." (PMID 33737928, 2021). "On the other hand, the frequency of both CD4+CD44+CD62L- and CD8+CD44+CD62L- T cells were increased at the peak of parasitemia." (PMID 32913355, 2020). "These inflammatory infiltrates are composed by cells like macrophages, CD4 + and CD8 + T lymphocytes and natural killer cells, being important for parasite clearance, thus controlling parasitemia." (PMID 33329529, 2020). "We monitored body weight, body temperature and parasitemia, measured SIV viral loads, hemoglobin and neopterin, and tracked the CD4+, CD8+, and CD4+ memory subpopulations, Ki67 and apoptosis by flow cytometry." (PMID 31718574, 2019). "Next, we directly compared the IFN-γ producing CD4+ and CD8+ T cells in PyNL infection around peak parasitemia." (PMID 31608052, 2019). "Both T cells (CD4+ and CD8+) regulate the healing of the host and the decrease of parasite infection through the reduction of host injuries." (PMID 31749567, 2019). "We observed a statistically significant cell-mediated immune response led by the production of CD4+ and CD8+ T cells before and after parasite infection." (PMID 30911415, 2019). "For example, parasite infection (Nb) and mite allergen (HDM) induced predominantly IL-10-producing LAG3+CD49b+ T cells that are CD4+ with very few that are CD8+." (PMID 30510554, 2018). "The study reveals that the depletion of Treg cells reduced the level of parasitaemia and increased the activation of CD4+ and CD8+ T cells, indicating that Treg cells play a crucial role in the control of immune responses to parasitic infection." (PMID 30126413, 2018). "P. berghei ANKA luc-infected anti-IL-10R antibody-treated mice presented peripheral parasitemia levels similar to those of mice given anti-CD8+, -CD4+, or -IFN-γ antibodies." (PMID 28396319, 2017). "Meanwhile, Ly49E KO mice harbored higher numbers of IFN-γ-positive NKT, CD4 T cells, and CD8 T cells than WT mice near the peak of parasitemia." (PMID 27891126, 2016). "We observed that depletion of CD4+ T cells alone, or depletion of both CD4+ and CD8+ T cells, rendered the mice unable to control parasitemia." (PMID 27245410, 2016). "In this study, we showed that rSSP4-primed CD4+CD25+ regulatory T cells play a decisive immunoregulatory function by decreasing inflammation and increasing survival and parasitemia in immunized and rSSP4-primed CD4+CD25+ T cells-transferred mice." (PMID 23509755, 2013). "The authors of the Zambian study suggest a CPT-related decrease in bacterial and parasitic infections as a mechanism for the reduction in preterm birth, a mechanism which may be less likely to impact birth outcomes in women in our study, who had higher CD4 cell counts." (PMID 24363547, 2013). "Comparison of models where protection from infection and time to onset of parasitemia depend on (i) anti-CSP antibodies and CSP-specific CD4+ T cells; (ii) anti-CSP antibodies only; (iii) CSP-specific CD4+ T cells only; and (iv) vaccination status only." (PMID 23613845, 2013). "It has been demonstrated that CD4+ T cells can prevent the exhaustion of CD8+ T cells during chronic viral and Plasmodium parasitic infections." (PMID 23071696, 2012). "Parasitemia correlates with a burst of monocyte-derived TGF-β production, increases in CD3+CD4+CD25hi T cells and FOXP3 expression." (PMID 22348117, 2012). "Abrogation of IL-10 and TGF-β response or depletion of CD4+CD25+ Treg cells restores the Th1 cytokine balance allowing the murine host to control and eradicate the parasitic infection." (PMID 22348117, 2012). "The data from a previous report in mice, which showed high parasitemia in CD4−/CD8+ animals and low parasitemia and high survival in CD4+/CD8+ mice, help to explain the results of this study." (PMID 21912712, 2011).